KRT75 (keratin 75)
Description:
Plays a central role in hair and nail formation. Essential component of keratin intermediate filaments in the companion layer of the hair follicle.
Synonyms: CK-75; hK6hf; K75; K6HF; KB18; PFB
Tractability: Antibody: its Gene Ontology location is reachable by antibodies, with medium confidence; the Human Protein Atlas places it where antibodies can reach. PROTAC: ubiquitination databases record sites on it.
Gene: Protein-coding gene on chromosome 12 (52,424,070 to 52,434,371, reverse strand). Ensembl gene ENSG00000170454.
Subcellular location (Human Protein Atlas): Cytosol; Plasma membrane
Pathways (Reactome):
Developmental Biology: Formation of the cornified envelope; Keratinization
Gene Ontology:
Molecular function: protein binding; structural constituent of skin epidermis; structural molecule activity
Biological process: intermediate filament organization; keratinization
Cellular component: extracellular exosome; intermediate filament; cytosol; keratin filament; cornified envelope
Genetic constraint (gnomAD): Loss-of-function variants: 37 observed, 50.16 expected, observed/expected ratio (o/e) 0.74, 90% interval 0.57 to 0.97. The upper end of that interval is the gene's LOEUF score, 0.97, which puts it in group 4 of 6, group 1 being the genes least tolerant of losing a copy. Missense variants: 764 observed, 720.19 expected, observed/expected ratio (o/e) 1.06, 90% interval 1 to 1.13. Synonymous variants: 300 observed, 286.13 expected, observed/expected ratio (o/e) 1.05, 90% interval 0.95 to 1.15.
Homologues: Orthologues: chimpanzee KRT75 (99% identical), macaque KRT75 (97% identical), pig KRT75 (87% identical), dog KRT75 (86% identical), guinea pig KRT75 (85% identical), mouse Krt75 (85% identical), rat Krt75 (83% identical), tropical clawed frog krt61 (66% identical), tropical clawed frog krt6b (34% identical). Paralogues in human: KRT5 (79% identical), KRT6A (74% identical), KRT6C (73% identical), KRT6B (73% identical), KRT76 (65% identical), KRT3 (63% identical), KRT1 (61% identical), KRT79 (60% identical), KRT2 (60% identical), KRT4 (58% identical), KRT77 (55% identical), KRT71 (55% identical), and 56 more.
Diseases named in the same sentence as KRT75 in open-access papers:
KRT75 is named in the same sentence as 24 diseases in open-access papers, as found by Europe PMC text mining. Sharing a sentence is not in itself a finding about the gene and the disease. The quoted sentences say what the papers report.
Pseudofolliculitis barbae (2 papers, 2012 to 2022). "Mutations in KRT75 have been associated with the hair disorderpseudofolliculitis barbae (PFB)." (PMID 22829773, 2012). "Interestingly, mutations in type II hard and soft hair keratins (KRT75, KRT81,83,85,86), but not type I hair keratins (KRT25-28, KRT31-40), have reported associations with other genetic hair disorders such as Monilethrix, pseudofolliculitis barbae, and hair ectodermal dysplasia." (PMID 35145093, 2022).
dental caries (1 paper, 2018). The decay of a tooth, in which it becomes softened, discolored, and/or porous. "According to recent studies, a set of keratins was incorporated into mature enamel, and keratin 75 mutations are associated with increased susceptibility to dental caries." (PMID 30359274, 2018).
fungal infections (1 paper, 2025). "The hair and nails with superficial fungal infections closely resemble the morphological abnormalities, including broken and rough hair shafts, as well as loosely attached and hypertrophic nails, in normally developing mice with mutations of Krt75, a member of the keratin family." (PMID 39498991, 2025). "Just as the role Krt75 plays in the pathogenesis of PFB, fungal infections may promote the formation of ingrown hairs through a similar mechanism, namely as rough and sharp ends close to the scalp and curly configurations of hairs." (PMID 39498991, 2025).
glioma (1 paper, 2022). A benign or malignant brain and spinal cord tumor that arises from glial cells (astrocytes, oligodendrocytes, ependymal cells). "Recent analyses also highlight that some keratin forms (KRT33B, KRT75) can be used as prognostic biomarkers for early detection of low-grade gliomas, and others (KRT75) can be used to reveal transformation tumors with higher probability to switch from low-grade gliomas to GB." (PMID 35454156, 2022).
hair disorders (1 paper, 2018). "We showed previously that the organic material in mature enamel is in part composed of epithelial hair keratins, and that missense mutations in KRT75, previously linked to common hair disorders, were associated with increased susceptibility to dental caries." (PMID 29357356, 2018).
hypotrichosis (1 paper, 2025). A congenital condition, usually due to genetic aberrations, that is characterized by a lack of hair growth on the head and/or body. "Specifically, KRT75, KRT71, and KRT25 (which were found to be increased in both gene sequencing and qPCR analysis) are involved in hair and nail development, with mutations in these genes linked to conditions such as wooly hair and hypotrichosis." (PMID 40843897, 2025).
hypotrichosis 8 (1 paper, 2023). Any hypotrichosis in which the cause of the disease is a mutation in the LPAR6 gene. "In addition, some paralog genes Krt25, Krt27, Krt72, Krt75, and Krt85, which also participate in the formation of keratin intermediate filaments in the IRS, could be related to Woolly Hair, Autosomal Recessive 3, and Hypotrichosis 8, which were significantly decreased in Krt71–KO mice." (PMID 37443815, 2023).
melanoma (1 paper, 2015). A malignant, usually aggressive tumor composed of atypical, neoplastic melanocytes. "For example mutations in α-keratin (KRT75) produce the pleiotropic effects in chicken and a cis-acting regulatory mutation in intron 6 of STX17 (syntaxin-17) is responsible for the pigmentation and melanoma susceptibility phenotypes in horse." (PMID 26100605, 2015).
oral cancer (1 paper, 2023). "Some of the DEGs common to OLP and oral cancer include KRT4 (down-regulated) and KRT16, KRT17, KRT10, and KRT75 (up-regulated)." (PMID 38234400, 2023).
psoriasis (1 paper, 2023). An autoimmune condition characterized by red, well-delineated plaques with silvery scales that are usually on the extensor surfaces and scalp. "A depletion of cytoskeletal keratin proteins (KRT14 and KRT75) possibly alleviates the psoriasis severity." (PMID 37495626, 2023).
tumor (3 papers, 2020 to 2022). "After removing the individual samples from the database, we obtained 20 pairs of paired samples and then compared the expression levels of CCL20, SCG5, SPP1, FOLR3, and KRT75 genes in tumor tissues vs. normal tissues." (PMID 36684241, 2022). "The genes TIMP1, MAGEB17, CA3, and KRT75 expressions are relatively lower with sequence read at <100 in both cultured cells and tumor samples." (PMID 33808801, 2021). "In univariate analysis, larger tumour size, with pharmaceutical drug adjuvant therapy, high FNCLCC grade, increased COL11A1, ITGA10 and KIF26B expression, and decreased CLEC3B, DUOX2, KRT75 and PPP2R2B were risk factors of shorter RFS." (PMID 31742892, 2020).
cancer (2 papers, 2008 to 2024). A tumor composed of atypical neoplastic, often pleomorphic cells that invade other tissues. "In addition, we also identified 6 upregulated genes not typically associated with cancer (ARC, C1orf167, CNGA3, KRT75, SPRR1B, STUM)." (PMID 38038766, 2024).
KRT75 also shares sentences with these, for which no sentence is quoted: infection (3 papers); anagen (1); cataract (1); colorectal cancer (1); ectodermal dysplasia (1); ependymoma (1); glioblastoma (1); monilethrix (1); spinal cord ependymoma (1); squamous cell carcinoma (1); supratentorial ependymoma (1); Woolly hair (1).